BRAF (B-Raf proto-oncogene, serine/threonine kinase)
Diseases named in the same sentence as BRAF in open-access papers (continued):
Sharing a sentence is not in itself a finding about the gene and the disease.
melanoma (continued). "However, the observation that DN tend to harbor non-V600E BRAF and NRAS mutations suggests that there are likely to be alternative pathways to Clark’s classically postulated model of a linear step-wise progression to melanoma." (PMID 31861163, 2019). "Hirata and colleagues have shown that melanoma-associated fibroblasts can drive resistance to the BRAF (v-Raf murine sarcoma viral oncogene homolog B) inhibitor vemurafenib by stimulating fibronectin production and remodeling, and subsequently promoting β1/Src/FAK pathway signaling in melanoma." (PMID 31109009, 2019). "Indeed, up to 80% of all melanomas harbor activating NRAS or BRAF mutations, with BRAFV600E representing more than 90% of BRAF mutations, resulting in constitutive activation of the signaling pathway, promoting melanoma proliferation and resistance to apoptosis." (PMID 31780644, 2019). "Therefore, we investigated the molecular targets that could be used to ameliorate and maximize the benefit from irradiation, particularly in BRAF mutant melanoma." (PMID 31374895, 2019). "This G-quadruplex ligand thus represents a suitable candidate for the development of melanoma treatment options based on a new mechanism of action and could reveal particular significance in the context of resistance to targeted therapies of BRAF-mutant melanoma cells." (PMID 31635389, 2019). "BRAF mutation can also represent a therapeutic target in metastatic CRC but targeting BRAF will also require the blockade of other pathways including, EGFR, MEK and PI3K differently from melanoma and non-small cell lung cancer where BRAF inhibition produces therapeutic benefits." (PMID 30736475, 2019). "The most important and frequent mutation of BRAF is V600E, which results in the substitution of the valine amino acid by glutamic acid at position 600, thereby dysregulating the activation map of the kinase/ERK signaling pathway, leading finally to melanoma genesis." (PMID 31531096, 2019). "Since large Japanese populations of melanoma subtypes are acral lentiginous melanoma (ALM) and mucosal melanoma, which have low levels of tumor mutation burden (TMB) and BRAF mutation, TMB might be correlated to the BRAF mutation rate." (PMID 31514399, 2019). "Hence, one can postulate that deregulation of autophagy could represent a protective mechanism to contrast the growth inhibitory effect of BRAF inhibition following UPMIRNAs overexpression in melanoma cells." (PMID 30254376, 2019). "Failures in the treatment of advanced melanoma require new approaches and a search for new therapeutic targets that may increase the effectiveness of therapy, similar to the discovery of the V600E BRAF mutant." (PMID 31091806, 2019). "Intense efforts have been directed to identify additional mechanisms of resistance, in particular adaptive non-genetic mechanism, which may help melanoma cells to survive the stress linked to the exposure to BRAF/MEK inhibitors." (PMID 31557826, 2019). "Although the use of BRAF inhibitor to target MAPK-dysregulated tumours was found to be a promising therapy, the response duration was limited owing mainly to the reactivation of MAPK by multiple mechanisms, as observed in melanoma, a typical BRAF-mutated tumour." (PMID 31126017, 2019). "Recently, two new type II BRAF inhibitors, vemurafenib (PLX4032/ Zelboraf®, Plexxikon and Genentech) and dabrafenib (GSK2118437/ Tafinlar®, GlaxoSmithKline), have achieved approval by the FDA for the treatment of metastatic and unresectable BRAF-mutated melanomas." (PMID 30975211, 2019). "This may be a result of enhancement of melanoma antigens with BRAF treatment." (PMID 31134073, 2019).
melanoma (continued). "The v-raf murine sarcoma viral homolog B1 (BRAF) inhibitor drug vemurafenib (PLX4032) is used to treat melanoma; however, epidemiological evidence reveals that it could cause cutaneous keratoacanthomas and squamous cell carcinoma in cancer patients with the most prevalent HRASQ61L mutation." (PMID 31242703, 2019). "However, BRAF mutation more frequently appears in melanomas in locations without chronic sun damage." (PMID 31890008, 2019). "Previous studies have shown that ErbB3 is a key factor in the development of adaptive resistance to BRAF and Mek inhibitors, albeit with different mechanisms, and that ErbB3 inhibition with monoclonal antibodies is able to potentiate the efficacy of target therapy in melanoma." (PMID 31557826, 2019). "Importantly, single-copy loss of ATG5 has been identified as a distinctive feature of advanced melanomas, regardless of the mutational status of melanoma associated-oncogenes (e.g., BRAF, RAS), and associated with poor overall patient survival." (PMID 31998652, 2019). "In addition, a part of melanoma patients with BRAFV600E mutation do not respond to BRAF inhibitors, which was regarded as primary resistance." (PMID 31134073, 2019). "Thus, BRAF-based peptide vaccine is a promising strategy for the BRAF-mutant melanoma therapy." (PMID 31617076, 2019). "This represents a crucial aspect as, it would indicate that immune evasion of BRAF-mutated melanoma cells may be reversed by a specifically targeted BRAF inhibition without affecting T-cell function." (PMID 31762942, 2019). "For example, melanomas and colorectal carcinomas may exhibit mutations in RAS, BRAF and MEK." (PMID 31046843, 2019). "The optimal treatment sequence for patients with advanced BRAF V600 mutant melanoma is unknown." (PMID 31677253, 2019). "These included 43 (9.6%) non-codon 600 BRAF mutations detected from 446 melanoma specimens." (PMID 31277584, 2019). "Therefore, we asked whether ZFP36 is necessary for NOXA mRNA decay upon BRAF inhibition in melanoma cells." (PMID 31727958, 2019). "Also, a previous preclinical study suggests that EGFR inhibitors may have different effects on melanoma cells depending on their mutational status, and that EGFR TKI-s especially in combination could be an effective approach to eliminate BRAF-mutant melanoma." (PMID 31514305, 2019). "Therefore, melanomas with class-2 or class-3 mutations are not expected to respond to current FDA-approved BRAF inhibitors, which are monomer selective." (PMID 31277584, 2019). "Also, closely connected cancer types share the same medication, e.g., Skin cancer and Melanoma are treated by Vemurafenib and Dabrafenib which are enzyme inhibitor of BRAF gene, Leukemia and Non-Hodgkin lymphoma are treated by the antibody Rituximab targeting B-lymphocyte antigen CD20." (PMID 31536541, 2019). "Furthermore, this study also suggested that targeting AhR signaling could prevent the induction of the BRAF inhibitor resistance gene in melanoma cells, thus augmenting the efficacy of BRAF inhibitors." (PMID 31514399, 2019). "Whole-exome and whole-genome sequencing of melanomas have shown many UV signatures in melanomas from sun-exposed body sites suggesting that some BRAF mutations can be caused by “non-informative UV-induced mutations” i.e., changes that do not occur at a dipyrimidine sites." (PMID 31552252, 2019). "However, MDM4 was found weakly expressed in mutant BRAF vemurafenib-resistant melanoma cell lines." (PMID 31374895, 2019). "As half of the advanced melanoma patients bear mutations at the residue Val 600 in the kinase BRAF that lead to constitutive activation of the MAPK pathway, targeted therapies including BRAF inhibitors (vemurafenib, dabrafenib) and MEK inhibitors (trametinib, cobimetinib) have been developed." (PMID 31023624, 2019). "BRAF inhibition could enhance melanoma antigen expression and facilitate T-cell cytotoxicity." (PMID 30939167, 2019).
melanoma (continued). "Similarly, the RAF/MEK treatment affects BRAF wild type melanoma cells and fibroblasts similarly by killing cells only at high concentration, suggesting that the non-targeted effect of the MEK inhibitor Trametinib kills cells indiscriminately and mainly at higher concentrations." (PMID 31138163, 2019). "Indeed, although BRAF inhibitors (BRAFi) are the most potent therapeutic drugs approved to counteract the melanoma cases displaying BRAF-mutated genotype, their use is not decisive because patients acquire resistance after 8–10 months of treatment." (PMID 31783660, 2019). "In comparison with patients without BRAF mutations, BRAF-mutated melanomas are more likely to metastasize to the brain and may have a worse outcome." (PMID 31039200, 2019). "The ongoing LOGIC-2 phase II clinical trial aims to find out whether targeting the FGF/FGFR signaling pathway with BGJ398 may be a good therapeutic strategy in melanoma patients who develop resistance to v-Raf murine sarcoma viral oncogene homolog B (BRAF)/MEK inhibitors." (PMID 31167513, 2019). "Although the standard procedures for detecting BRAF mutations are DNA-based, IHC has many advantages: IHC requires less tumor tissue, detects BRAFV600E mutations in specimens with low tumor content, and enables visualization of the location of mutated melanoma cells." (PMID 31817947, 2019). "However, the efficacy of targeted agents varies widely based on the tumor type; e.g., the combination of BRAF and MEK inhibitors is known to be highly effective in melanoma patients with BRAFV600 mutations, while it has limited efficacy in colorectal cancer patients." (PMID 31570099, 2019). "To understand how sRNA alterations might contribute to the development of resistance to BRAF inhibitors in 451Lu melanoma cells that carry BRAFV600E mutations, we undertook a sRNA sequencing study of cells before and after the establishment of BRAF inhibitor resistance." (PMID 30349559, 2018). "Still, there were developed melanoma models using hairless mice subjected to DMBA (7,12-dimethylbenzanthracene)—as initiator agent and UV irradiation promoter, and transgenic mice carrying BRAF mutations (increased risk to develop melanoma when UV irradiation was added)." (PMID 29795011, 2018). "We show that PI3K/AKT activating mutations in melanoma do not enable proliferative escape in response to combination BRAF and MEK inhibition, but rather allow the survival of a dormant sub-population of MAPK-inhibited tumour cells, that remain under selective pressure to reactivate MAPK signalling." (PMID 30237495, 2018). "Moreover, targeted treatment options in melanoma subtypes without activating BRAF mutations are limited." (PMID 30188888, 2018). "However, our clinically relevant preclinical PDTX mouse models confirm and support the conclusion that BRAF/MEK inhibitors combined with CDK4/6 inhibitors effectively inhibits tumor growth in BRAFV600E-mutant melanomas by simultaneous or subsequent targeting of the cell cycle machinery." (PMID 29541385, 2018). "Next, we asked whether the dependence of A375X1 melanoma cells on ALK could be exploited to overcome BRAF inhibitor resistance and we treated the cells with three different ALK inhibitors (Crizotinib, Ceritinib and ASP3026) alone or in combination with PLX4032." (PMID 30290811, 2018). "Consistent with this, in BRAF-mutated non-small cell lung cancer (NSCLC) and melanoma, YAP-dependent expression of BCL2L1 allows cancer cells to escape from apoptosis under BRAF- or MEK-targeting therapy, even though it has not been examined whether β-catenin is involved in this process." (PMID 30101371, 2018).
melanoma (continued). "MAPK pathway activation and cell cycle dysregulation are general hallmarks of melanoma resulting from aberrations in cell proliferation, deficiency of the retinoblastoma protein (pRb), mutations in CDK4, and overexpression of cyclin D1 following resistance to BRAF inhibition." (PMID 29541385, 2018). "Mutations of the main RTKs transducer—RAS/BRAF—are events more frequent than mutations in RTKs, yet, mutated forms of RTK genes including KIT, ERBB1-4, PDGFR, the EPH and FGFR families, and others are known to govern abnormal signaling driving aberrant growth and survival of melanoma cells." (PMID 29946532, 2018). "Hence, we attempted to address whether Phd2 haplo-deficiency in melanocytes is still capable of cooperating with oncogenic BRAF to induce melanoma in our experimental setting." (PMID 30575721, 2018). "However, the fact that inhibition of BRAF mutated at V600 is effective in melanoma but not in colorectal cancer is a prominent example against the general transferability of knowledge on a single actionable mutation from one histological tumor type to another." (PMID 30442178, 2018). "For example, our finding that the MEK inhibitor Cobi used as a single agent can inhibit the lytic capacity of T cells might be of importance in studies using MEKi without BRAFi in the setting of melanoma with non-mutated BRAF but mutated NRAS." (PMID 29346301, 2018). "Considering the close integration among all these pathways and MAPK signaling as well as several reports that exhibit the regulation of autophagy in BRAF mutant melanoma, we hypothesized that extracellular signal-regulated kinase (ERK) may contribute to the regulation of autophagy in our model." (PMID 29581864, 2018). "Moreover, melanoma cells made resistant to the BRAF inhibitor vemurafinib, which acts upstream of MEK activation and signalling, exhibited activated SRC signalling in vitro and in vivo, and exhibited sensitivity to SRC inhibition by both dasatinib and saracatinib." (PMID 29435137, 2018). "EC activity against both Erk and Akt pathways may explain, at least partially, why in all three melanoma cell lines investigated, EC had the same potency, regardless of BRAF mutation status." (PMID 29772645, 2018). "We speculate that the differentiation status of wildtype NRAS/BRAF melanomas impacts on the prognostic utility of ICAM-1, as more than three quarters of the wildtype NRAS/BRAF tumors had high PMEL levels and thus were derived from well differentiated melanocytes." (PMID 30116025, 2018). "Therefore, even if the mutant BRAFV600E was inhibited by Vemurafenib/PLX4032, melanoma cells still could activate the MAPK pathway through wild-type BRaf." (PMID 29464040, 2018). "Hence, the best treatment sequencing of targeted and immunotherapy for patients with BRAF-mutated melanoma and normal LDH is not clear." (PMID 30002656, 2018). "Besides targeted therapy, immunotherapy has been shown to induce a significant and durable clinical benefit in a limited subset of melanoma patients, providing the rationale for testing BRAF/MEK targeting agents along with immune-checkpoint inhibitors in the clinical settings." (PMID 29682188, 2018). "Finally, BRAF mutations typically occur in younger patients [14••], are less associated with the UV mutation signature, and are more prevalent in melanomas arising on not chronically sun-exposed skin areas." (PMID 30218391, 2018). "Further studies are needed to confirm that eNAMPT is a marker of disease burden and possibly an independent negative prognostic factor in BRAF-mutated MM patients, as well as a critical element in the induction of immunosuppressive and tumor-promoting conditions in the melanoma microenvironment." (PMID 29721178, 2018).
melanoma (continued). "TGFβ-induced epithelial-to-mesenchymal-like transition (EMT-like) has been described in melanoma recently and is characterized by melanoma cells switching from a proliferative phenotype to an invasive phenotype which is accompanied by induced drug-resistance to BRAF and MEK inhibitor treatment." (PMID 29541007, 2018). "Therefore, uncoupling of OXPHOS to perturb energy homeostasis and to indirectly stimulate AMPK could be a novel treatment for melanoma and to overcome intrinsic and acquired resistance to BRAF inhibitors." (PMID 30651927, 2018). "These treatments may be effective against melanoma regardless of the mutation status of BRAF or NRAS, if the tumors are resistant to targeted treatments, or are in relapse from immunotherapy." (PMID 30185782, 2018). "BRAF mutations are very common in cutaneous melanoma and trigger MAPK pathway activation (60% of the cutaneous melanomas exhibit MAPK activating mutations), whereas in other types of melanoma, such as acral, mucosal, conjunctival, and uveal, its incidence is quite low." (PMID 29795011, 2018). "Melanomas arising on skin without chronic sun-induced damage often harbour BRAF p.V600E mutations, while those arising on skin with chronic sun-induced damage typically harbour other BRAF mutations." (PMID 30412573, 2018). "In addition, we demonstrated that miR-550a-3-5p treatment could sensitize BRAF inhibitor-resistant colon cancer and melanoma cells." (PMID 29844307, 2018). "Similarly, quantitative analysis of tumor associated mutant BRAF extracellular DNA revealed that higher overall response rate to BRAF inhibitors and longer progression free survival were seen in melanoma patients with lower concentration of basal mutant BRAF extracellular DNA." (PMID 30243303, 2018). "Interestingly, these types of BRAF mutations have been reported in carcinoma and melanoma, but not in other histiocytic tumors." (PMID 30084011, 2018). "Next, to determine whether expression of any of these genes are regulated by MAPK signaling in melanoma, we analyzed their expression by quantitative real-time PCR (qRT-PCR) after treatment with the BRAF inhibitor vemurafenib (PLX4032) in the BRAF (V600E) mutant melanoma cell line WM164." (PMID 29880484, 2018). "Among the selective serine/threonine kinase inhibitors, BRAF inhibitors (Vemurafenib and Dabrafenib) and MEK inhibitors (Trametinib and Cobimetinib) are widely used in clinical practice for the treatment of mutated BRAFV600E melanomas, providing significant improvement in survival rates." (PMID 30483135, 2018). "ABCB5 may be associated with resistance in some but not all BRAF inhibitor-resistant melanoma cell lines." (PMID 29929490, 2018). "In particular, inhibitors of the cytoplasmic serine/threonine kinase BRAF and the immune-checkpoint targeted agents, anti-cytotoxic T-lymphocyte-associated antigen 4 (CTLA-4), and anti-programmed cell death 1 (PD-1) inhibitors have been approved for the treatment of advanced melanoma." (PMID 30693134, 2018). "Moreover, blocking E2F1 also induced death of melanoma cells resistant to BRAF inhibitors." (PMID 29743521, 2018). "A study of the RICTOR locus by CGH array in a series of 43 melanoma short-term cultures showed that RICTOR was amplified in 19 out of 43 melanoma cell lines (44%) and that amplification was independent of the BRAF and NRAS mutation status, the most frequent mutations in melanoma." (PMID 29455662, 2018). "Although the two currently approved combinations of BRAFi and MEKi appear similarly effective against melanoma, their effects on healthy cells, not bearing BRAF mutations, but employing the respective signaling pathway, may significantly differ." (PMID 29346301, 2018).